CRP (C-reactive protein)
Diseases named in the same sentence as CRP in open-access papers (continued):
Sharing a sentence is not in itself a finding about the gene and the disease.
pneumonia (continued). "In the univariate logistic regression analysis, S1P concentration was predictive of pneumonia with odds ratio of 1.27 (95% CI: 1.17–1.41; p < 0.0001) and CRP levels was predictive of pneumonia with odds ratio of 1.59 (95% CI: 1.35–1.99, 1.43–3.51 p < 0.0001)." (PMID 35307030, 2022). "Dyspnea was present in 191 (42.7%) pneumonia patients, respiration rates > 20/min was present in 201 (45.0%) pneumonia patients, and CRP > 20 mg/l was present in 259 (57.9%) pneumonia patients." (PMID 36253753, 2022). "Aside from pulse oximetry, there is insufficient evidence supporting the inclusion of other point-of-care tests (eg, CRP) as part of routine triage of children with chest-indrawing pneumonia." (PMID 36040992, 2022). "Cytokine and CRP levels as well as WBCs and lymphocyte counts were considered surrogate markers of severe lung affection and pneumonia in COVID 19 patients." (PMID 36675695, 2022). "In this study, in head-to-head comparisons, both PCT and CRP were inferior to sTREM-1 in predicting mortality in children with pneumonia." (PMID 35830474, 2022). "Multivariate analysis, including clinical symptoms and biomarkers, suggested that CRP ≥15.8 mg/dL at day 1 was a only promising predictor of pneumonia in AECOPD." (PMID 35400078, 2022). "With regard to clinical measures, SRSq was associated with C reactive protein (CRP), respiratory function (P/F ratios), and SOFA, as well as with pneumonia indexes estimated by DeCOI investigators." (PMID 36322631, 2022). "The increase in C-reactive protein is due to a post-traumatic stress response or recessive infection, such as hypostatic pneumonia or urinary tract infection." (PMID 35831810, 2022). "We found that the plasma levels of CRP ≥ 15.8 mg/dL are independent predictive factors of pneumonia in AECOPD." (PMID 35400078, 2022). "The length of antibiotic therapy was assessed by findings of elevated infection parameters, blood test results, C reactive protein (CRP) values, blood culture findings (all inoculated media remained sterile) and X-ray findings in pneumonia." (PMID 35888683, 2022). "Pneumonia was found to be correlated with CRP and fibrinogen levels, whereas hypoxia was correlated with LDH and CRP levels." (PMID 35669915, 2022). "Analysis of laboratory data performed on the day of admission showed higher levels of glycemia (p = 0.004), leukocytes (p < 0.001), neutrophils (p < 0.001), creatinine (p < 0.001), CRP (p < 0.001), and troponin T (p < 0.001) in the patients with pneumonia." (PMID 36430028, 2022). "In children with community-acquired pneumonia, CRP in severe pneumonia is significantly higher than in mild pneumonia." (PMID 35601429, 2022). "CRP was also an independent predictor of platelet aggregation and aspirin non-responsiveness in patients with acute coronary syndrome complicated by pneumonia." (PMID 35743540, 2022). "Further analysis was performed combining positive LUS with high C reactive protein for the diagnosis of acute pneumonia." (PMID 36553089, 2022). "This CRP response corresponding to pneumonia development was attenuated in statin( +) patients, although the rate of postoperative pneumonia correlated significantly with statin medication." (PMID 36104793, 2022). "CRP in healthy individuals is generally ≤ 5mg/L but in patients with pneumonia the levels can be >100mg/L." (PMID 36211412, 2022). "The good value of CRP for pneumonia prediction shown in our AFRI patients is consistent with previous reports." (PMID 36253753, 2022). "Patients with Adv+ pneumonia showed elevated CRP levels and PCT levels < 0.05 ng/ml; however, 5 patients (16.7%) showed elevated PCT levels (> 0.5 ng/mL)." (PMID 36161612, 2022). "Another study showed that CRP was significantly increased in children with acute lymphadenopathy during chemotherapy for severe pneumonia." (PMID 35601429, 2022).
pneumonia (continued). "Compared to patients with mild and moderate pneumonia, severely ill patients had higher CRP and MDA but lower plasma prooxidants TOS and O2− and antioxidants TAS, SOD, and PON1 levels." (PMID 36420478, 2022). "CRP concentrations was significantly higher in pneumonia patients than in non-pneumonia patients (t = 6.9, P < 0.0001)." (PMID 36253753, 2022). "On the other hand, as an important biomarker, C-reactive protein (CRP) plays a significant role in predicting pneumonia." (PMID 35509104, 2022). "On the basis of the blood biochemical index, children with severe pneumonia exhibited high levels of CRP, IL‐6, PCT, and D‐dimer." (PMID 35665444, 2022). "The results of this single-center pilot randomized controlled clinical trial show that an individualized biomarker-guided corticosteroid dosing approach in pneumonia using CRP is feasible and safe with high adherence to the study protocol." (PMID 34983600, 2022). "A 2019 commentary suggests using a combination of signs and symptoms and biomarkers (for example, C reactive protein levels) in making a clinical diagnosis of pneumonia." (PMID 34980049, 2022). "Several studies have showed CRP had a significant advantage in the diagnosis of pneumonia among patients with acute cough or lower respiratory tract infection." (PMID 36253753, 2022). "Patients in the COVID group generally had lower signs of inflammation (CRP 12.2 mg/L), which is consistent with the majority of published data which also applies to the incidence of pneumonia and pleural effusions in the COVID group." (PMID 36670627, 2022). "The level of serum C-reactive protein tended to increase in patients with influenza, and it was significantly higher in the pneumonia group than in the non-pneumonia group (P < 0.05)." (PMID 35382755, 2022). "PCT and CRP are becoming more widely used in the management of febrile pediatric syndromes and in particular pneumonia." (PMID 35830474, 2022). "This study demonstrates that COPD patients with pneumonia presented significantly higher blood CRP lever and higher blood S1P compared to patients with AECOPD." (PMID 35307030, 2022). "Logistic regression and ROC analysis identified the effect of ESR on mortality and the sensitivity and specificity of the optimal cutoff values of ESR for the prediction of pneumonia, intensive care needs, and mortality and compared these with values for CRP." (PMID 35992514, 2022). "Oxygen saturation was increased, pneumonia severity index was markedly improved and there was a substantial decrease in C reactive protein (between 15.1–1.23 over 4 days)." (PMID 36358582, 2022). "Baseline LDH activity and C-reactive protein (CRP) concentrations were higher in patients who died from pneumonia than in those who survived." (PMID 35740079, 2022). "The aim of this study was to evaluate the value of S1P and CRP for discriminating COPD with pneumonia and AECOPD in an Emergency Department (ED) setting." (PMID 35307030, 2022). "DRC model is a simple tool for pneumonia prediction that is composed of items on dyspnea, respiration rates > 20 /min, and CRP > 20 mg/l." (PMID 36253753, 2022). "Most common serious infection was pneumonia (n = 164), with a median CRP of 48 mg/L (IQR 13–113), followed by gastroenteritis with DH (n = 162, median CRP 9.5 mg/L, IQR < 5–30) and complicated UTI (n = 58, median CRP 54.5 mg/L, IQR 22–127)." (PMID 36333682, 2022). "Sensitivity and specificity values for pneumonia, intensive care requirements, and mortality were lower than those for CRP." (PMID 35992514, 2022). "There were significant differences between the two groups in CRP, pneumonia complications (alveolar fluid), and race type (p < 0.05)." (PMID 36683805, 2022). "This diagnostic is powered by noninvasive measurements of host-derived protease activity, a means of pneumonia classification distinct from the oft-cited biomarkers such as CRP, PCT, and inflammatory cytokines." (PMID 35696579, 2022).
pneumonia (continued). "According to previous studies, AST, ALT, LDH, and CRP levels and various cytokines are considered potentially valuable biomarkers for severe or refractory pneumonia." (PMID 36205104, 2022). "The cause of fever, leukocytosis, and elevated C‐reactive protein (CRP) level was thought to be pneumonia at the time of admission; however, autopsy examination revealed that it was due to an ovarian tumor complicated by an abscess." (PMID 36408084, 2022). "In our study performed on patients with severe forms of pneumonia, we found that ESR has a higher correlation with fibrosis than CRP (Spearman’s rho 0.422 vs. 0.252) with a higher risk of fibrosis (5.7% vs. 1.5% for 1 unit increase in the variable)." (PMID 36010377, 2022). "The univariate analysis revealed 14 significant variables (age, plt count, alb, AST, ALT, LDH, CK, CRP, ferritin, and D-dimer levels, DM, anorexia, presence of pneumonia, and third wave), which were included in the multivariable logistic regression analysis." (PMID 36505104, 2022). "Other studies showed a good prognostic value of Hp and Lpc-2 to distinguish severe pneumonia due to malaria from those of bacterial and viral origin, while few studies found CRP to be a good biomarker in the current coronavirus pandemic (COVID-19)." (PMID 36036460, 2022). "Pneumonia patients had a longer hospital stays than other patients, and C-reactive protein (CRP) levels in pneumonia patients were higher than those in other patients." (PMID 35875560, 2022). "In summary, LMR and NLR showed better validated discriminative accuracy than other biomarkers (LC, NC, MC, WBC and CRP), either in distinguishing the overall pneumonia from URTI or in discriminating subgroups of viral or bacterial pneumonia from URTI." (PMID 34861849, 2021). "The existing body of evidence is not convincing that PCT adds anything beyond what other, cheaper biomarkers (like C-reactive protein) or clinical assessment can provide for management of paediatric pneumonia." (PMID 34704032, 2021). "Some patients with extreme bilateral pneumonia have elevated levels of aspartate aminotransferase, creatine kinase, creatinine, C-reactive protein (CRP), D-dimers, and ferritin." (PMID 34205487, 2021). "The children with RSV (+) pneumonia were younger (p = 0.026) and had lower C-reactive protein (p = 0.003) and household crowding (p = 0.012) than the RSV (-) group, after controlling for confounding covariates." (PMID 34306103, 2021). "Attention should be paid to kidney health of children with CAP especially in presence of higher duration of symptoms before hospitalization, severe pneumonia and higher serum CRP levels." (PMID 33745060, 2021). "Twenty years ago a study of 72 children hospitalized with CAP found greater positive and negative predictive values of PCT than other biomarkers, including C-reactive protein and WBC count, for differentiating bacterial and viral causes of pneumonia." (PMID 34704032, 2021). "Blood test revealed: white blood cell count (WBC) 27 × 109/L, band neutrophils 27% of WBC, CRP 450 mg/L, also, chest X‐ray showed bilateral pneumonia." (PMID 33155427, 2021). "Certainly, markers of inflammation such as CRP, IL-6, or ferritin were significantly elevated among patients with pneumonia." (PMID 34728695, 2021). "Model A was based on the presence of ischemia and pneumonia; Model B was based on age > 65 years, high supplemental oxygen requirement, and elevated CRP values." (PMID 34270604, 2021). "The higher observed CRP values in the historical pneumonia cases probably relates to the fact that a substantial proportion of community-acquired pneumonias are caused by a bacterial pathogen." (PMID 33174170, 2021). "We found that duration of symptoms before hospitalization, severity of pneumonia, and serum CRP levels were significant and independent predictors for AKI in children with CAP." (PMID 33745060, 2021).
pneumonia (continued). "The following cut-off points were observed for the biomarkers in predicting pneumonia from asymptomatic state: serum ferritin = 636.25 μg/l; D-dimer = 0.8 μg/ml; and CRP = 26.4 mg/l." (PMID 33988463, 2021). "For some variables fewer than 148 data values were available: among these were (available numbers for analysis in parentheses): race/ethnicity, SES, ischemia, pneumonia, CRP, BNP." (PMID 34270604, 2021). "Children with RSV (+) pneumonia were younger (<2 years) and had lower CRP (<20 mg/dL) and interstitial infiltrates in the CXR than RSV (-) pneumonia." (PMID 34306103, 2021). "CRP is an important biomarker that can reflect the severity of pneumonia and the injury in extra-pulmonary tissues." (PMID 33479472, 2021). "The decreased number of lymphocytes, and the increased levels of CRP, LDH, d-dimer, and fibrinogen levels are associated with SARS-CoV 2 related pneumonia." (PMID 33832103, 2021). "Main prognostic factors for AKI are represented by duration of symptoms before hospitalization, severity of pneumonia, and serum CRP levels." (PMID 33745060, 2021). "Laboratory tests showed an increase in C-reactive protein (154 [37.8%]), and radiological tests showed pneumonia with peripheral ground-glass pattern (172 [51.4%])." (PMID 34933389, 2021). "Il-6 and CRP values upon admission, severe pneumonia, the highest oxygen flow value and infection with the variant alpha were associated with either death or transfer to the ICU in univariate analysis." (PMID 34441844, 2021). "Duration of symptoms before hospitalization (OR 1.2; 95%CI 1.09–1.43; p = 0.001), severe pneumonia (OR 11.9; 95%CI 4.3–33.3; p < 0.001), and serum C-reactive protein levels (OR 1.1; 95%CI 1.04–1.23; p = 0.004) were independent AKI predictors." (PMID 33745060, 2021). "Two models (Model A: two variables, presence of pneumonia and ischemia); (Model B: three variables, age > 65 years, supplemental oxygen ≥ 4 L/min, and C-reactive protein (CRP) > 10 mg/L) were selected and tested in the validation cohort." (PMID 34270604, 2021). "CRP was significantly higher in the pneumonia group than the control group (mean 37.48 ± 32.72 and 3.29 ± 2.50 mg/l, respectively, P < 0.001)." (PMID 34708133, 2021). "Very recently, Tsai and colleagues reported that salivary IL-6 and CRP levels are significantly higher in pediatric patients with pneumonia compared to healthy controls." (PMID 34708133, 2021). "A final multivariate analysis including all these parameters showed that only duration of symptoms before hospitalization, severe pneumonia, and CRP levels were independent predictors of AKI." (PMID 33745060, 2021). "Several studies have researched mortality predictors in patients with SARS-CoV-2-induced pneumonia, and identified age, cardiovascular and metabolic comorbidities, and C-reactive protein (CRP) as significant prognosis factors." (PMID 35011795, 2021). "Modern molecular immunology believes that the inflammatory response will stimulate the liver to synthesize CRP in large amounts through factors such as IL-6, so its level will be significantly higher in children with pneumonia." (PMID 34956578, 2021). "A study involving seven countries showed that the increase of CRP was positively correlated with bacterial pneumonia and negatively correlated with pneumonia infected by a virus." (PMID 34836530, 2021). "More importantly, the correlation findings documented the levels of MEG3 were closely associated with neutrophils, CRP, and PCT, punctuating the clinical significance of MEG3 in severe pneumonia." (PMID 34558385, 2021). "Combined with CRP, PA can effectively improve the diagnostic efficiency of children’s CAP and assess the severity of pneumonia." (PMID 33441105, 2021). "In adults, factors predicting development of AKI include severity of pneumonia, elevated CRP, and previous need of angiotensin-converting enzyme inhibitors or angiotensin-II-receptor blockers." (PMID 33745060, 2021).
pneumonia (continued). "On laboratory testing, children with pneumonia had higher leukocyte counts and C-reactive protein (CRP), D-dimer, interleukin-6 (Il-6) and alanine as well as aspartate aminotransferase (ALT and AST) levels than patients without pneumonia." (PMID 34768620, 2021). "For some variables fewer than 100 data values were available; among these were (available numbers for analysis in parentheses): race/ethnicity, SES, ischemia, pneumonia, CRP, BNP." (PMID 34270604, 2021). "Twenty-seven patients with pneumonia and 19 asymptomatic had all the values of CRP, serum fibrinogen, serum ferritin and D-dimers." (PMID 33988463, 2021). "Moreover, serum lactate and biomarkers such as C-reactive protein and procalcitonin may be associated with severe outcomes in childhood pneumonia and may be considered for implementation in future mortality risk assessment tools in settings where these tests are available." (PMID 34737862, 2021). "We observed that serum ferritin followed by D-dimer had better predictive accuracy in identifying patients with pneumonia compared with asymptomatic; and CRP in addition had better accuracy for predicting severe illness compared with mild-moderate." (PMID 33988463, 2021). "The best performing score in this regard was the 4C, which requires both urea, C-reactive protein, a lymphocyte count as well as a Chest-X-ray to determine the presence of pneumonia." (PMID 34689760, 2021). "Of those 16 virally infected patients with clinical signs of bacterial pneumonia (lobar pneumonia detected by chest radiograph or pneumonia with CRP higher than 200 mg/L), 94% (15/16) had an increased (≥ 0.36) FCBI-index value (range: 1.40–7951, median: 22)." (PMID 34844193, 2021). "They included rural residency, CHD, history of pneumonia, cough, cyanosis, dyspnea, abnormal chest X-ray, hypoalbuminemia, elevated CRP, and proteinuria (P < 0.05)." (PMID 33892752, 2021). "In summary, a single initial serum measurement of the biomarkers (PCT and CRP) have a limited value to predict mortality in critically ill patients with influenza pneumonia." (PMID 33810263, 2021). "All patients were referred for CXR when the physician ́s suspicion of pneumonia was ‘unsure’, or ‘quite sure’ after CRP-testing." (PMID 32705941, 2020). "Tachycardia, pneumonia, presence of malignancy, high SAPS3 score, persistently elevated CRP, and cardiac troponin were associated with mortality in this study." (PMID 32155161, 2020). "Severe pneumonia patients showed higher levels of CRP and hs-CRP in the first 7 days of analysis, suggesting that SARS-CoV-2 has bacterial infection characteristics." (PMID 33065551, 2020). "If the physician is unsure in the primary judgement, the outcome is more likely to remain unsure or lower to exclude pneumonia after CRP." (PMID 33399009, 2020). "Premorbid baseline ADL impairment, fever during hospitalization, and increased CRP at admission were predictors of severe pneumonia in elderly patients with COVID-19 infection in multivariate logistic regression analysis." (PMID 33291617, 2020). "Patients with SARS-CoV2 treated for pneumonia with Toculizumab had a marked decrease in the inflammatory markers such as CRP and ferritin, along with significant clinical improvement post-infusion." (PMID 33101164, 2020). "In primary care, CRP improves the assessment of the severity of infection and extent of inflammation and performs better in predicting the diagnosis of pneumonia than any individual or combination of clinical signs and symptoms." (PMID 32070390, 2020). "In a retrospective study including elderly patients (median age 81 years) hospitalized for an acute respiratory infection, AUROCs for the diagnosis of pneumonia were 0.76 for CRP and 0.54 for PCT." (PMID 32997689, 2020). "Studies have demonstrated higher specificity (93 to 96%) and sensitivity (75 to 91%) of serum CRP at levels ranging from 48 to 200 mg/L in diagnosing pneumonia." (PMID 32709677, 2020).